LINC02864 (long independently transcribed non-coding RNA 2864)
Synonyms: RP11-169F17.1
Gene: Long non-coding RNA gene on chromosome 18 (73,150,105 to 73,264,533, reverse strand). Ensembl gene ENSG00000263711.
Diseases named in the same sentence as LINC02864 in open-access papers:
LINC02864 is named in the same sentence as 1 disease in open-access papers, as found by Europe PMC text mining. Sharing a sentence is not in itself a finding about the gene and the disease. The quoted sentences say what the papers report.
co-infection (1 paper, 2024). "Interestingly, LINC02864, found to be dysregulated across all the HCMVPosGC data sets, was specifically upregulated when there was a co-infection of HCMV and EBV." (PMID 39283078, 2024).